TMEM198 (transmembrane protein 198)
Description:
Promotes LRP6 phosphorylation by casein kinases and thereby plays a role in Wnt signaling. May be a membrane scaffold protein involved in the self-aggregation of LRP6 to further enhance its activity.
Synonyms: MGC99813; TMEM198A
Tractability: Antibody: its Gene Ontology location is reachable by antibodies, with high confidence; UniProt places it where antibodies can reach, with medium confidence; UniProt predicts a signal peptide or a membrane-spanning region.
Gene: Protein-coding gene on chromosome 2 (219,543,130 to 219,550,595, forward strand). Ensembl gene ENSG00000188760.
Subcellular location: Membrane; Cell membrane; Cytoplasmic vesicle
Subcellular location (Human Protein Atlas): Vesicles
Gene Ontology:
Biological process: positive regulation of canonical Wnt signaling pathway
Cellular component: cytoplasmic vesicle; plasma membrane; membrane
Genetic constraint (gnomAD): Loss-of-function variants: 15 observed, 20.17 expected, observed/expected ratio (o/e) 0.74, 90% interval 0.5 to 1.14. The upper end of that interval is the gene's LOEUF score, 1.14, which puts it in group 5 of 6, group 1 being the genes least tolerant of losing a copy. Missense variants: 368 observed, 356.54 expected, observed/expected ratio (o/e) 1.03, 90% interval 0.95 to 1.12. Synonymous variants: 190 observed, 166.87 expected, observed/expected ratio (o/e) 1.14, 90% interval 1.01 to 1.28.
Homologues: Orthologues: chimpanzee TMEM198 (99% identical), macaque TMEM198 (99% identical), dog TMEM198 (99% identical), pig TMEM198 (98% identical), mouse Tmem198 (98% identical), rat Tmem198 (98% identical), zebrafish tmem198ab (60% identical), zebrafish tmem198aa (56% identical), tropical clawed frog TMEM198 (44% identical), Drosophila melanogaster CG14234 (23% identical).
Diseases named in the same sentence as TMEM198 in open-access papers:
TMEM198 is named in the same sentence as 5 diseases in open-access papers, as found by Europe PMC text mining. Sharing a sentence is not in itself a finding about the gene and the disease. The quoted sentences say what the papers report.
COVID-19 (1 paper, 2021). A disease caused by infection with severe acute respiratory syndrome coronavirus 2. "TMEM198 has been associated with diabetes as observed in comorbidities of COVID-19 symptomatic cohorts included in the study." (PMID 34566994, 2021).
viral infection (1 paper, 2025). "Gene deletion of TMEM198 led to a reduction in the levels of viral infection in cells, whereas the ectopic expression of TMEM198 correspondingly resulted in an increase in infection levels." (PMID 40446005, 2025). "Our study is the first report to demonstrate the functional correlation between TMEM198 and viral infection." (PMID 40446005, 2025). "We observed viral titers in TMEM198 knockout cells were significantly reduced during viral infection." (PMID 40446005, 2025). "Knockout of TMEM198 dramatically inhibit viral infection and delay the progression of diseases." (PMID 40446005, 2025).
infection (1 paper, 2025). The state of being infected such as from the introduction of a foreign agent such as serum, vaccine, antigenic substance or organism. "We also observed that infection with MHV in TMEM198−/− mice significantly delayed disease progression and markedly reduced viral titers." (PMID 40446005, 2025). "The results from immunofluorescence and qPCR analyses revealed that the levels of TGEV N protein were significantly reduced in TMEM198 knockout cells following infection with TGEV at an MOI of 0.01." (PMID 40446005, 2025). "We assessed the viral titer in the liver tissue of both WT and TMEM198−/− mice at 5 days post-infection." (PMID 40446005, 2025). "Western blot analysis indicated that, at MOIs of 0.01 and 0.001, the TGEV-encoded N protein was either barely detectable or weakly expressed in TMEM198 knockout cells compared to Ctrl cells at 36h post-infection." (PMID 40446005, 2025). "Based on high similarity of amino acid of TMEM198 across different species and nsp3/nsp4 from various coronaviruses, we hypothesize that TMEM198 may serve as a broad-spectrum host factor involved in the infection processes of multiple coronaviruses." (PMID 40446005, 2025). "To determine whether TMEM198 affects TGEV viral genome replication, we monitored the total viral genomic RNA (gRNA) during the early stages of infection." (PMID 40446005, 2025).
TMEM198 also shares sentences with these, for which no sentence is quoted: colon cancer (1 paper); diabetes (1).